CCL20 (C-C motif chemokine ligand 20)
Diseases named in the same sentence as CCL20 in open-access papers (continued):
Sharing a sentence is not in itself a finding about the gene and the disease.
tumor (continued). "Previous studies have reported that the chemokine CCL20 facilitates the recruitment and retention of CCR6+Treg cells, thereby promoting tumor invasion and progression." (PMID 38311726, 2024). "We performed a 6-color mIHC staining on tissue microarray (TMA) samples to evaluate the tumor area and the densities of VDR overexpression cells, CCL20 overexpression cells, M2 macrophages and M1 macrophages." (PMID 38600588, 2024). "The expression of CCL20 and PLAU significantly differed between primary tumours and solid normal tissues and in survival curves by the Kaplan–Meier method." (PMID 38363001, 2024). "Particularly, in HCC the IDO upregulation by pDCs was mediated by HIF-1α/CCL20/STAT1 pathway, promoting tumor tolerance and metastatization." (PMID 39020402, 2024). "Chemokines chemokine C-C motif ligand (CCL) 9 (CCL9), CCL17, CCL20, CXCL5, CXCL9, and CXCL10 secreted by hepatocytes regulated tumor progression by acting on CD8+ T cells." (PMID 39346534, 2024). "High levels of CCL20 are secreted by tumor cells and KCs to which CCR6 expressed in Tregs gets attracted inducing the migration towards the tumor site." (PMID 38571964, 2024). "In addition, it was found that the increased level of autophagy resulted in the release of more chemokine CCL20 from prostate cancer cells, which could recruit more macrophages for infiltration and induce their polarization to M2 type for the regulation of the tumor immune microenvironment." (PMID 39703512, 2024). "CCL20 has been shown to promote CD163 expression in macrophages and induce TAM infiltration as well as M2-like macrophage polarization in tumor tissues." (PMID 39776914, 2024). "Juzentaihoto treatment as well as the combination treatment (but not Gemcitabine treatment alone) showed a significant increase of the macrophage chemoattractant chemokines CCL2/MCP-1, CCL20/MIP3α, and CXCL2/MIP-2 in the supernatant of tumor cells." (PMID 39723364, 2024). "Our study revealed elevated expression of supernatant CCL20 in tumor cells, and the effect of overexpression of VDR tumors on macrophages disappeared after we blocked CCL20." (PMID 38600588, 2024). "In tumor regions, the expression levels of CCL2, CCL5, CCL20, CXCL9, CXCL10, CXCL11 and CXCL12 were generally higher in hot tumors than in the other two groups." (PMID 37847338, 2024). "Chemokines and cytokines, such as IFN-γ, CXCL9, and CCL20, are related to the recruitment of CD4+ and CD8+ T cells, so the lack of chemokines and cytokines may lead to impaired recruitment of immune cells, thereby causing an immunosuppressive tumor microenvironment." (PMID 38982511, 2024). "Breast tumors recruit CD1a+ immature dendritic cells by releasing CCL20 and then instruct those immature dendritic cells to prime IL-13 secreting CD4+ T cells that facilitate tumor development." (PMID 38786066, 2024). "In clinical samples analysed by TCGA, the expression of 5 genes, CCL20, IL1B, IL24, PLAU and SEMA7A, was significantly higher in the primary tumour than in solid normal tissue, whereas that of CITED2 was lower." (PMID 38363001, 2024). "It binds to miR-1322, enhancing CCL20 secretion, which interacts with CCR6 on TAMs, facilitating tumor cell and TAM communication that promotes tumor progression." (PMID 38249783, 2024). "Consistently, the p65, CCL20, and Ki-67 expressions in tumor xenografts were repressed after ABLIM1 knock-down, supporting ABLIM1 modulates the IĸBα/NF-κB/CCL20 axis to promote CRC progression." (PMID 38228802, 2024). "CCL20, a CCR6 ligand, attracts CCR6-expressing Tregs, promoting tumor progression and unfavorable outcomes in HCC." (PMID 39000453, 2024). "All APC-targeting pDNA vaccines conferred superior tumor control compared to the mock control with CCL19, CCL20, and CCL21_Neo5 displaying statistically significant improvements." (PMID 37720215, 2023).
tumor (continued). "P38 was significantly activated through the CCL20/CCR6 axis, and then p38 played a signal transduction function to modify the miRNA spectrum, thereby creating conditions for the metastasis of tumor cells." (PMID 36447119, 2023). "For the further investigation of the expression of the three genes (CCR3, CCL14, CCL20) in HCC tissues, RT-qPCR was applied to the detection of mRNA expression of the three genes between HCC tissues and adjacent non-tumor tissues." (PMID 37545521, 2023). "Among the monocyte clusters, Mono_2 cluster derived from the tumor tissue (VCAN, THBS1, and CCL20) was found to play an important immunosuppressive role." (PMID 37533434, 2023). "These high SCFA concentrations led to Th17 cell recruitment by inducing C-C motif chemokine ligand 20 (CCL20) expression in the lung; subsequently, Th17 cells inhibited tumor proliferation and metastasis." (PMID 37100764, 2023). "In this study, we discovered for the first time that CCL20 modulated the PMN-MDSC expansion in BM, blood, spleen and tumor, promoting tumor immune-suppressive microenvironment." (PMID 36859354, 2023). "In CRC patients, Fn promotes macrophage infiltration by activating tumour-derived CCL20 while inducing M2 macrophage polarisation and enhancing CRC metastasis through the miR-1322/CCL20 axis." (PMID 38143746, 2023). "Subsequently, we extracted total RNA from different tumor cell lines (SMMC7721, Huh7, HepG2, and HCCLM3) and the normal liver cell lines (WLR68, and LO2) to measure the mRNA expression levels of CCL20, and SLC7A2." (PMID 36969014, 2023). "Compared with healthy individuals, CCL20 levels were higher in BC, attracting immune cells that express CCR6 near the tumor." (PMID 37373025, 2023). "The RT-qPCR results demonstrated remarkable discrepancies in the expression of CCL14, CCL20, and CCR3 between HCC and its paired adjacent non-tumor tissues." (PMID 37545521, 2023). "Th17 cells are generated by tumor-derived IL1β and IL13, and accumulate in tumor tissues in response to various chemokines, including CCL2, CCL5, CCL20, CCL17, CCL22, and MIF, which are produced from tumor cells." (PMID 36211375, 2022). "Downregulated expression of CCL20 can repress EMT signaling pathways in LUAD cells and restrain tumor growth." (PMID 35864953, 2022). "Among them, several studies demonstrated that the interaction of CCL20 and CCR6 promoted the tumor progression in melanoma, breast cancer, and hepatocellular carcinoma via enhancing angiogenesis." (PMID 35642002, 2022). "Immature DCs can be recruited into the TME, attracted by tumor-secreted factors such as CCL2, CCL20/MIP3a, CCL25, CCL5, CXCL12, CXCL1, and CXCL5, while mature DCs reside in areas surrounding the tumor." (PMID 35267487, 2022). "In EBV-positive NPC cells, activated NF-kB regulates a number of chemokines (CXCL9, CXCL10, CX3CL1, and CCL20), which recruit tumor-infiltrating T lymphocytes and modulate the NPC tumor environment." (PMID 36289760, 2022). "Among CCL chemokines, CCL2, 3, 4, 7, and 8 were significantly less secreted by tumor tissues, while CCL17, CCL20, and CCL22 were secreted in higher concentrations in tumor as compared to juxta-tumor tissues." (PMID 36539890, 2022). "In some analogy to the enhanced CCL20-driven Treg recruitment during neoadjuvant chemotherapy, surgical interventions might also bear the risk of promoting local Treg accumulation in CRC and thereby tumor progression, with CCL18 discussed as the responsible chemokine." (PMID 36428508, 2022). "The tumor-infiltrating lymphocytes most closely related with CEMIP expression in BC were CCL7, CCL14, CCL20, and CXCL14." (PMID 35370456, 2022). "Some proteins, such as IL22, CCL20, and MMP9, all shown to be involved in tumor progression were exclusively higher in serum from rats with MLL-tumors." (PMID 35551231, 2022). "The RORγt agonist promoted Type 17 T cell migration by upregulating CCL20 and CCR6 expression as well as Type 17 T cell tumor infiltration, improving the efficacy of anti-PD-1." (PMID 35459193, 2022).
tumor (continued). "CCL20 works by binding to CCR6 receptors present on DCs, which are involved in the recruitment of numerous inflammatory cells and suppression of tumor cells proliferation." (PMID 35408440, 2022). "In EC, the B7/CTLA-4 signaling pathway activates the tumor or matrix derived from chemokines (e.g., CCL20 (C-C motif chemokine ligand 20)), activating and recruiting Treg." (PMID 36106333, 2022). "During hyperthermia, cells under heat stress enhance immune response by promoting the release of more exosomes rich in tumor antigens, chemokines (including CCL2, CCL3, CCL4, CCL5 and CCL20, etc.)and HSP to APC to identify and destroy tumor cells." (PMID 36032103, 2022). "CCL20 thus allows the recruitment of CCR6+ CD4 immunosuppressive T cells (Th17, Treg) at the tumor site and favors the migration and the metastatic potential of CCR6-expressing cancer cells from diverse types." (PMID 36429101, 2022). "The same applies to CCL20, which has been described to induce Epithelial-Mesenchymal-Transition (EMT) in PDAC cells, thereby promoting tumor cell migration and invasion and finally leading to metastasis." (PMID 36230528, 2022). "The expression of CCL20, CD70, PCDH7, DCBLD2, and MMP14 genes were remarkably more elevated within LUAD samples than adjacent non-tumorous tissues, where PIK3R5, RNF144B, BTG2, CD69, and MEP1A genes were the opposite." (PMID 36497225, 2022). "In fact, the expression of key neutrophil-secreted chemokines, including CCL3, CCL4, CCL20, and CXCL12, was increased in the tumor supernatants of mice treated with 7HP349." (PMID 35552271, 2022). "EBV nuclear antigen 1 (EBNA1) induce the production of CCL20, or MIP-3α to promote chemotaxis of Tregs to the tumor site." (PMID 35311066, 2022). "We found that high CCL20 mRNA expression in tumor tissues significantly indicated shorter DFS and OS for LUAD patients, which further confirmed that CCL20 can be used to monitor and predict clinical outcomes in LUAD patients." (PMID 35642002, 2022). "Chemokines, such as CCL20 and CXCL14, can recruit DCs to tumor tissue to inhibit tumor proliferation and metastasis." (PMID 36230972, 2022). "A similar strategy that combined CCL20 and CD40L was adopted resulting in an enhanced growth suppression of TERT-positive tumor cells." (PMID 33802281, 2021). "In this study, we further verified that CCL5 and CCL20 were significantly upregulated in both HCC cell lines and tumor tissues compared with normal controls by Western blot and IHC, which were consistent with the transcriptional levels." (PMID 34938730, 2021). "Tregs recruitment occurs through the binding of CCR4 on Tregs surface and CCL22 secreted by GBM tumour cells and CD163+ TAMs, under the induction of tumour-derived CCL20 and osteoprotegerin." (PMID 33804731, 2021). "Tumor-infiltrating neutrophils can support adaptive immune responses by recruiting T cells to tumor sites via the secretion of chemokines, such as CCL5, CCL20, CXCL9, CXCL10 and CXCL11." (PMID 34572138, 2021). "Different chemokines, such as CCL5 and CCL19, have been expressed in various types of virus; in particular, CCL20 and CCL21 have shown to enhance anti-tumor effects when used to arm Onc.Ads." (PMID 33802281, 2021). "CCL20+ TAMs can also secrete tumour necrosis factor-alpha (TNFα) and vascular endothelial growth factor-A (VEGF-A), contributing to tumour growth and angiogenesis." (PMID 34830780, 2021). "For example, the macrophage pro-inflammatory chemokines CCL20 and MIP3α bind to CCR6 on the surface of PDAC cells to upregulate MMP9 expression and tumor invasion." (PMID 34201127, 2021). "A transcriptomic analysis of human tumor liver tissue showed an increased expression of several chemokines, such as CCL20, CXCL10, and CXCL11, compared with adjacent non-tumor liver tissue." (PMID 35008212, 2021).
tumor (continued). "These included IL-12p70, pro-inflammatory IL-1β, and TNF, as well as MIP-3α (CCL20) and MIP-3β (CCL19), which are chemotactic for lymphocytes and DCs, and IFN-α, which is known to activate antigen presentation for T cell-mediated tumor cell recognition." (PMID 34912334, 2021). "The expression level of CCL20, F2, GNPNAT1 and NT5E in the tumor samples was significantly higher than that in normal tissues, while the expression level of B3GALT2, and VSIG2 displayed an opposite expression pattern." (PMID 34787244, 2021). "Examples of cytokines and growth factors induced by TLR2 and/or TLR4 in OSCC cells include IL-1, IL-6, GM-CSF, TNF-alpha, CCL2, CCL20, CXCL8, and VEGF, which contribute to the inflammatory environment, vascularization, and tumor cell properties." (PMID 35048056, 2021). "It develops in response to tumor-derived factors and releases IL10, IL12, TNFα, TNFβ, VEGF, CCL20, CCL22, and MMP9, thereby supporting tumor growth and metastases and acting as an immunosuppressant." (PMID 32900001, 2020). "To further investigate the role of CCL20 in FDPS‐mediated macrophage infiltration, we treated the mice bearing control or FDPS‐overexpressing tumour with CCL20 neutralizing antibody." (PMID 32596949, 2020). "The same study has found that CCL20 produced by HCC cells recruits CCR6+CD5+ B cells and induces angiogenesis to promote tumor growth and that blocking CCL20 suppressed angiogenesis." (PMID 32707869, 2020). "This resulted in the expression of the pro-inflammatory cytokines and chemokines CCL20, CXCL1, IL-8, and TFF1 leading to the recruitment of macrophages in the tumor microenvironment and of vasculogenic endothelial cells to promote angiogenesis." (PMID 32373132, 2020). "Using the TCGA database, we analysed MAP3K8, CCL20, VEGFC, and ANGPTL4 gene expression levels in both normal tissue and tumour tissue samples." (PMID 32019546, 2020). "Western blotting, qRT-PCR, and enzyme-linked immunosorbent assay were used to evaluate chemokine ligand 20 (CCL20) and colony stimulating factor 1 (CSF-1) expression in FOXO1(+) and FOXO1(-) tumor cells." (PMID 33052231, 2020). "Many studies have shown that the CCL20/CCR6 axis contribute to the initiation and progression of HCC by mediating the migration of circulating T cells into the tumor microenvironment." (PMID 32256215, 2020). "Thus, the role of CCL20 in tumor development may be tumor specific." (PMID 32508847, 2020). "In agreement, shRNA-mediated of CCL20, CXCL1, or TFF1 depletion in CFPAC-1 pancreatic cancer cells significantly decreased the percentage of macrophages that interact with tumor cells in vivo, while IL-8 depletion reduced CD31+ endothelial cell recruitment." (PMID 32373132, 2020). "The mRNA expression of CYP1A1 (p = 0.002), CCL20 (p = 0.047), p19 (p = 0.029), CCL19 (p = 0.013), IL-36γ (p = 0.0076), and IL-17 (p = 0.0035) was significantly decreased in tumor from AhR-(fl/fl) Krt5-(Cre) mice compared with wild type mice." (PMID 33178182, 2020). "Others reported that CCL20 was capable of inducing epithelial-mesenchymal-transformation (EMT) in HCC cells, promoting the engraftment of tumor cells." (PMID 32508847, 2020). "Chemokine axes such as CCL19, CCL21/CCR7, CCL20/CCR6, CXCL12/CXCR4, and CXCL13/CXCR5 correlate with B cell infiltration to tumor sites." (PMID 31991604, 2020). "It has been shown that the genes encoding chemokines CCL20, CXCL8/IL-8, and the adhesion molecule L-selectin are overexpressed in PTC in comparison to normal thyroid, independently from the RET/PTC or BRAF status, suggesting that these chemokines could be associated with tumor-related inflammation." (PMID 31500315, 2019). "For instance, RET/PTC induces the expression of oncogenes involved in inflammation and tumor invasion, such as chemokines (CCL2, CCL20, CXCL8/IL-8, and CXCL12), chemokine receptor CXCR4, and cytokines (IL-1B, colony-stimulating factor 1, and GM-CSF)." (PMID 31500315, 2019).
tumor (continued). "In qRT-PCR, CCL20 mRNA expression in tumor tissues was significantly greater than in NATs (P = .01) and FOXP3 mRNA expression in tumor tissues was also significantly greater than in NATs (P = .02)." (PMID 31852159, 2019). "As our data indicate, TAMs likely secrete CCL20, and CCR6-expressed RCC cells consume CCL20 in the tumor microenvironment of RCC, resulting in an increased migration ability of the RCC cells." (PMID 31905918, 2019). "STING agonist upregulated the T cell chemokine CXCL10 with little effect on the DC attractant CCL20, suggesting that STING agonist therapy increases the adaptive anti-tumor T cell responses through multiple cellular mechanisms." (PMID 31036082, 2019). "Our studies showed that CCL20 stimulated the proliferation, invasion, and anchorage-independent growth in TNBC and promoted tumor outgrowth in vivo." (PMID 30052635, 2018). "A model combining the top three markers, CCL20, CXCL19 and PD-L1, discriminated tumor EBV status with an AUC of 0.82." (PMID 30142953, 2018). "The tumour tissue of a lesion, which was excised at 9 days after ASML PDAC cell implantation showed increased expression of Mmp2 and decreased expression of Ccl20 when compared to cells grown under cell culture conditions." (PMID 30603057, 2018). "Both CCL17 and CCL20 attract CC chemokine receptor 4 positive (CCR4+) Treg and Th2 cells to HL tumor cells in vitro." (PMID 29652813, 2018). "In a tumor microenvironment, Th9 cells were found to produce CCL20, which facilitate the migration of CCR6+ leukocytes in the tumor tissue." (PMID 29867972, 2018). "CCL20 had been reported to induce EMT, and is correlated with tumor formation, metastasis, or progression in many malignant neoplasms such as colorectal cancer and hepatocellular carcinoma." (PMID 29212174, 2017). "HCC cells did express higher CCL20 levels than non-tumour cells, and the main FOXP3+ Tregs assembled in CCL20 high-expressing area." (PMID 27725696, 2016). "In CRC tissues, the main source of CCL20, a ligand for CCR6, is considered to be TAM, and CCL20 secreted from TAM recruits CCR6+ T-reg to the tumor site, which synergistically promotes tumor progression in mouse models." (PMID 27136535, 2016). "With infusion of in vitro-generated Th17 cells, lungs of mice bearing B16 melanoma tumors had elevated dendritic cell and activated T cell recruitment, as well as elevated CCL20 and CCL2 expression, chemokines known to recruit these anti-tumor immune cells." (PMID 27784305, 2016). "Because the omental tumor tissues expressed high mRNA levels of CCL20 instead of CXCL1/2, we compared chemokine network in the omental tumor tissues with that in the parental cells (SKA and SKCXCR2 cell line)." (PMID 27723802, 2016). "It is shown that miR-21-5p directly target the tumor-suppressor PTEN, chemokine gene CCL20 and PDCD4." (PMID 26462034, 2015). "We found that 7 genes (IFITM1, SMAD6, TBX15, CHST4, LRRC4, CCL20, and NQO1) showed significantly different promoter methylation levels between tumor and non-tumor tissue (P value < 0.001) in approximately 80 % of the 78 HCCs." (PMID 26300991, 2015). "Using this approach, 7 genes were identified as undergoing tumor-specific aberrant promoter methylation in HCC, including IFITM1, SMAD6, TBX15, CHST4, and LRRC4 with hyper-methylated promoters and CCL20 and NQO1 with hypo-methylated promoters." (PMID 26300991, 2015). "Th17 cells stimulate tumor residential cells to produce CCL2 and CCL20, which provokes the recruitment of dendritic cell, granulocyte, CD4+ T cell, CD8+ T cell, and NK cell to the tumor site." (PMID 24872958, 2014). "Supportive of the importance of NF-κB signaling in the pathogenesis of this tumor was our finding that 4 NF-κB target genes, IL-11, CXCL5, VEGFC, and CCL20, are on the list of strongly expressed genes from our gene expression profiling analysis." (PMID 24223206, 2013).